AIRE (autoimmune regulator)
Diseases named in the same sentence as AIRE in open-access papers (continued):
Sharing a sentence is not in itself a finding about the gene and the disease.
autoimmune polyendocrine syndrome type 1 (continued). "Similarly, human patients with dysfunctional AIRE gene suffer from a devastating Autoimmune polyendocrine syndrome type 1 (APS1)." (PMID 27776542, 2016). "Autoimmune polyendocrinopathy candidiasis ectodermal dystrophy (APECED), formerly known as autoimmune polyendocrine syndrome type 1, is a paradigm of a monogenic autoimmune disease caused by mutations of a gene, named autoimmune regulator (AIRE)." (PMID 27597936, 2016). "Autoimmune polyendocrinopathy candidiasis ectodermal dystrophy (APECED), formerly known as autoimmune polyendocrine syndrome type 1 (APS-1), is a rare disease caused by mutations of the autoimmune regulator (AIRE) which acts as a transcription regulator that promotes immunological central tolerance." (PMID 27597936, 2016). "Autoimmune polyendocrine syndrome type 1 (APS-1, APECED) is a rare monogenic disorder caused by biallelic AIRE mutations and is classically associated with chronic mucocutaneous candidiasis (CMC), hypoparathyroidism, and adrenal insufficiency." (PMID 41009535, 2025). "Autoimmune polyendocrine syndrome type 1 (APS-1), also known as APECED, is a monogenic inborn error of immunity typically caused by biallelic deleterious variants of the autoimmune regulator (AIRE) gene." (PMID 35003106, 2021). "Autoimmune Polyglandular syndrome type 1 (APS1) or Autoimmune Polyglandular-Candidiasis-Ectodermal Dystrophy (APECED; OMIM #240300) is an autoimmune syndrome caused by monogenic mutations in the AIRE gene that result in defects in AIRE-dependent T cell education in the thymus." (PMID 32410729, 2020). "Mice with a defect in the autoimmune-regulator (AIRE) gene also possess a defective central tolerance and develop a murine-autoimmune polyendocrine syndrome type 1 (APS-1)." (PMID 27916939, 2016). "Autoimmune polyendocrine syndrome type 1 (APS-1), also known as autoimmune polyendocrinopathy–candidiasis–ectodermal dystrophy (APECED), is a rare monogenic disorder caused by biallelic mutations in the autoimmune regulator (AIRE) gene on chromosome 21q22.3." (PMID 41009535, 2025). "Monogenic autoimmune polyendocrine syndrome type 1 (APS-1), or autoimmune polyendocrinopathy-candidiasis-ectodermal dystrophy (APECED), caused by AIRE mutations, exemplifies a lifelong predisposition to multiple endocrine autoimmune targets, notably hypoparathyroidism and Addison’s disease." (PMID 41465179, 2025). "These multiple findings of targeted autoimmunity to endocrine tissues could not be explained by mutations in the AIRE gene, the cause of autoimmune polyglandular syndrome type 1, characterized by chronic candidiasis and several autoimmune diseases involving mainly endocrine tissues." (PMID 34889280, 2021). "Loss of function mutations in AIRE (either recessive or dominantly inherited) cause autoimmune polyendocrine syndrome type 1 (APS1, also known as autoimmune polyendocrinopathy-candidiasis-ectodermal dystrophy, APECED) by reducing or removing this function of AIRE in the thymus." (PMID 30888520, 2019). "Autoimmune polyendocrine syndrome type 1 (APS 1), also known as autoimmune polyendocrinopathy-candidiasis-ectodermal dystrophy (APECED), is a rare autosomal recessive disease caused by pathogenic variants in the autoimmune regulator (AIRE) gene." (PMID 25361846, 2014). "Loss-of-function AIRE single mutations are responsible for a very rare autosomal recessive disease named autoimmune polyendocrinopathy, candidiasis, and ectodermal dystrophy (APECED), or autoimmune polyendocrine syndrome type 1 (APS-1)." (PMID 21647405, 2011). "Disruption to the AIRE gene leads to impaired negative selection and multi-organ autoimmunity, manifesting in humans as the rare condition autoimmune polyendocrinopathy candidiasis ectodermal dystrophy (APECED)." (PMID 35241125, 2022).
autoimmune polyendocrine syndrome type 1 (continued). "Autoimmune polyendocrine syndrome type 1 (APS-1), also known as autoimmune polyendocrinopathy–candidiasis–ectodermal dystrophy (APECED), is a monogenetic autoimmune disease with an estimated prevalence of 1:100,000 caused by mutations in the autoimmune regulator (AIRE) gene." (PMID 34572460, 2021).
Autoimmunity (107 papers, 2006 to 2026). The occurrence of an immune reaction against the organism's own cells or tissues. "Loss-of-function mutations in AIRE disrupt this process, enabling the persistence of autoreactive lymphocytes and promoting widespread autoimmunity with a characteristic autoantibody profile." (PMID 41009535, 2025). "Some studies have highlighted that certain AIRE mutations exert pathogenic effects in a dominant fashion and show variable penetrance and degrees of autoimmunity." (PMID 41190326, 2025). "Three different proteins whose loss of function leads to severe autoimmunity, AIRE, FEZF2, and CHD4, have been shown to drive the expression of non-redundant sets of peripheral tissue antigens in mTECs." (PMID 38635416, 2024). "Patients with immunodeficiencies or autoimmunity where genetic analyses revealed heterozygous AIRE mutations were included in the study and the dominant-negative effects of the AIRE mutations were functionally assessed in vitro." (PMID 37235056, 2023). "AIRE is a critical transcription factor for shaping immunological tolerance and preventing autoimmunity, and its pathogenic variants are associated with autoimmune diseases." (PMID 36979710, 2023). "Deficiency or mutation in the AIRE gene can lead to an improper presentation of self-antigens and can also lead to problems with autoimmunity." (PMID 36483902, 2022). "Prediction of autoimmunity by the SNS model is mainly based on the studies on AIRE deficiency or mutation associated with multi‐organ autoimmunity." (PMID 36239215, 2022). "Although AIRE polymorphisms are associated with the development of organ-specific autoimmunity, the study of this topic in systemic autoimmune diseases seems to be interesting." (PMID 34621318, 2021). "Autoimmune polyendocrine syndrome type I (APS-1) is a monogenic model disorder of organ-specific autoimmunity caused by mutations in the Autoimmune regulator (AIRE) gene." (PMID 34526996, 2021). "The AIRE expression in the perinatal age window is important since it is necessary and sufficient to avoid autoimmunity characteristic of AIRE-deficient mice." (PMID 33923792, 2021). "This form features very few, if not unique, milder autoimmune manifestations, and its discovery suggests that dominant AIRE mutations play a previously unrecognized role in the induction of common organ-specific autoimmune disorders." (PMID 33729987, 2021). "A recent murine study showed that mutations in p100 degron underlie autoimmunity through AIRE-independent defects of thymic tolerance, which are largely mediated by changes in the thymic epithelium, including thymic medullary hypoplasia." (PMID 33815417, 2021). "At this point, one would expect that AIRE deficiency lead invariably to overt pancreatic-islet β-cell autoimmunity." (PMID 29483906, 2018). "Patients with AIRE mutations are susceptible to Candida albicans infection and present with autoimmune disorders." (PMID 29666621, 2018). "Bi-allelic mutations of AIRE are associated with an autoimmune disease that is similar to the spectrum of autoimmunity observed in DS." (PMID 29678139, 2018). "We screened all participants for the seven genes known to cause monogenic autoimmunity that can include diabetes (AIRE, IL2RA, FOXP3, LRBA, STAT1, STAT3, STAT5B)." (PMID 29417186, 2018). "More recently with the discovery that APECED is a monogenic disorder due to mutations in the AIRE gene, the involvement of allelic variants of the AIRE gene in autoimmunity in general was postulated." (PMID 27420045, 2016). "AIRE gene variants, especially in heterozygosity or sequence polymorphisms, were suspected to influence the development of certain organ-specific autoimmune disorders by affecting the establishment of tolerance at the thymus level in perinatal age." (PMID 27420045, 2016). "This analysis of the impact of AIRE deficiency on human B cells has revealed a signature pattern of humoral autoreactivity with general implications for our understanding of autoimmunity." (PMID 27426947, 2016).
Autoimmunity (continued). "A previous study using AIRE-deficient mice provided evidence that autoimmunity, provoked by dysfunction of AIRE, is thymic stroma-dependent." (PMID 23986760, 2013). "Specific loss of AIRE-dependent thymic expression of a single antigen leads to the development of autoimmunity in the organ where this antigen is expressed." (PMID 22506061, 2012). "AIRE encodes a potent repressor of autoimmunity and can cause severe autoimmune disease when mutated." (PMID 21750684, 2011). "Depending on their genetic background, AIRE −/− mice exhibit several signs of peripheral autoimmunity, which are associated with a significant decrease in thymic transcription of neuroendocrine genes (including Ot, Npy, Igf2, and Ins2), as well as other TSAs." (PMID 21647405, 2011). "A literature review identified 25 rare heterozygous AIRE variants previously reported in association with autoimmunity, including variants described as dominant-negative or partially inhibitory, 13 of which were observed in UKB, collectively carried by 2123 participants." (PMID 42262224, 2026). "This suggests a potential link between effective AIRE activity and associated autoimmunity." (PMID 39440452, 2024). "AIRE variants were detected in the DNA of patients affected by organ-specific autoimmune disorders." (PMID 38473903, 2024). "AIRE gene monoallelic mutations located in the first plant homeodomain (PHD1) zinc finger with autosomal dominant inheritance were found associated with autoimmune disorders with later onset, milder phenotype, and reduced penetrance that did not satisfy the clinical diagnostic criteria for APECED." (PMID 38473903, 2024). "It is generally recognized that genetic variability in the AIRE locus and the presence of heterozygous loss of function AIRE mutations can affect the presentation of self-antigens in the thymus and thus the development of certain organ-specific autoimmune disorders." (PMID 38473903, 2024). "AIRE also participates in the positive selection of thymic regulatory T cells and mouse studies have shown that defective neonatal output of thymic regulatory T cells in AIRE deficiency contributes to the development of organ-specific autoimmunity." (PMID 34790633, 2021). "AIRE deficiency impairs mTEC maturation and prevents expression of Aire-dependent TRAs, resulting in failed central tolerance and export of autoreactive T cells that induce multi-organ autoimmunity." (PMID 33968086, 2021). "AIRE gene mutation and polymorphisms have been linked to several autoimmune disorders." (PMID 34621318, 2021). "Interestingly, autosomal-dominant defects in AIRE have now been reported, raising the possibility of more prevalent single gene causes of autoimmunity." (PMID 29686669, 2018). "However, more research is needed to determine the contributions of such AIRE variants to autoimmune susceptibility, especially in kindreds with a strong family history of autoimmunity." (PMID 27597936, 2016). "In DS the predisposition to autoimmunity may result from a partial central tolerance failure due to insufficient intrathymic expression of AIRE gene, which is located on chromosome 21." (PMID 25971674, 2015). "According to this view, the thymus of DS patients might contain significantly lower levels of AIRE gene, which may in turn condition the predisposition to autoimmunity that is typical of DS." (PMID 25971674, 2015). "In fact, in mice where TEC do not produce miRNA due conditionally inactivate Dgcr8 gene, there is a specific loss of mature mTEChi and AIRE+ subsets that induce a breakdown in thymic central tolerance with the presence of autoantibodies or development of spontaneous autoimmunity." (PMID 26347748, 2015). "Because the effects of AIRE-deficiency are so drastic, many studies have addressed the possibility that heterozygous mutations or genetic variants of AIRE might also predispose to autoimmunity." (PMID 24109480, 2013).
Autoimmunity (continued). "However, several recent studies suggest that single-nucleotide polymorphisms in the AIRE gene are associated with an increased risk of autoimmunity, including rheumatoid arthritis and vitiligo." (PMID 24109480, 2013). "Comparative transcriptomic analyses of TRA expression in the thymi of AIRE‐deficient rats and mice reveal that while AIRE regulates a similar set of self‐antigen genes across rodent species, certain distinctions exist that may account for species‐specific differences in autoimmunity." (PMID 41461613, 2026). "This may impair the ability to suppress autoimmunity caused by AIRE deficiency." (PMID 38632993, 2024). "However, more subtle reduction in AIRE function can also predispose to autoimmunity." (PMID 37235056, 2023). "AIRE polymorphism identification may indeed act as a marker to emphasize the need to look for additional or novel genetic determinants playing in concert in causing polyautoimmunity and autoimmunity-immunodeficiency-associated conditions." (PMID 35683627, 2022). "The presentation of self-antigens in the thymus that might favor the development of certain organ-specific autoimmune disorders is also conceived to be influenced by genetic variability in the AIRE locus and the presence of heterozygous loss-of-function mutations of the AIRE gene." (PMID 35683627, 2022). "Remarkably, the AIRE gene is upregulated contrary to expectations of either neutral or downregulation in the case of PCD’s association with autoimmunity; upregulation could be potentially due to a variety of factors, including epigenetics and crosstalk among molecular pathways." (PMID 36483902, 2022). "However, heterozygous AIRE mutations - including V301M - may hide behind common autoimmune disorders, and lead to variable clinical manifestations among family members." (PMID 35058929, 2021). "Furthermore, AIRE-deficient mTEC showed a specific reduction in promiscuous transcription of genes encoding peripheral antigens, demonstrating the importance of thymus-dependent tolerance in controlling autoimmunity." (PMID 21647405, 2011). "One mechanism by which estradiol enhances autoimmunity is through ERα-mediated downregulation of the Autoimmune Regulator (AIRE) gene, a central element of thymic tolerance." (PMID 41283475, 2025). "Surprisingly, this revealed that sera from individuals with anti-Mi2 autoantibodies also recognize autoimmune regulator (AIRE), a protein whose dysfunction leads to autoimmunity." (PMID 40568090, 2025). "The transcription factor AIRE plays a key role in autoimmunity by promoting the ectopic expression of peripheral tissue-restricted antigens in the medullary epithelial cells of the thymus." (PMID 40507919, 2025). "The autoimmune regulator (AIRE) is another candidate immune-related gene that develops multiple tissue-specific autoimmunities by inducing adverse selection of T cells in the thymus." (PMID 39459398, 2024). "The AIRE gene has a regulatory role on the autoreactive T cells in the thymus, whereas defects in the gene have been found to generate tissue-specific autoimmunity." (PMID 39459398, 2024). "More recently, it was reported that mice lacking the expression of both PD-1 and the autoimmune regulator (AIRE) genes developed fatal adulthood autoimmunity." (PMID 39062968, 2024). "Because of its unique function, AIRE has been the focus of extensive research efforts with the overall aim of improving our understanding of how autoimmunity can arise." (PMID 39440452, 2024). "Importantly, some of these AIRE mutations were found to a relatively high frequency in the general population and particularly in families with recurrent autoimmunity, suggesting that AIRE variants may modulate the phenotypic expression of common organ-specific autoimmune diseases." (PMID 39440452, 2024). "From 2016, eight heterozygous point mutations were identified within the PHD1 and PHD2 domains of AIRE in 11 patients with symptoms of autoimmunity or immunodeficiencies." (PMID 37235056, 2023).